KIT (KIT proto-oncogene, receptor tyrosine kinase)
Diseases named in the same sentence as KIT in open-access papers (continued):
Sharing a sentence is not in itself a finding about the gene and the disease.
systemic mastocytosis (continued). "Indeed, additional germline variants in KIT and in genes encoding for cytokines or their receptors (e.g., IL13, IL6, IL6R, IL31, IL4R), as well as increased copy numbers of the TPSAB1 gene encoding for α‐tryptase, have been increasingly recognized as associated with systemic mastocytosis in adults." (PMID 41177946, 2025). "A case report of systemic mastocytosis and mastocytemia in a cat identified an ITD in exon 8 of KIT." (PMID 38787171, 2024). "However, there are also rare cases of classic systemic mastocytosis without KIT mutation." (PMID 39456668, 2024). "A KIT D816V mutation has been found in approximately 90% of patients with systemic mastocytosis (SM), irrespective of WHO SM subtype." (PMID 26796887, 2016). "Nevertheless, in aggressive systemic mastocytosis and suspected well differentiated systemic mastocytosis cases, demonstration of absence of D816V is clinically important since cases with wild type-KIT and certain types of KIT mutations other than D816V may respond to imatinib therapy." (PMID 24141298, 2013). "It is characterized by elevated numbers of immature atypical mast cells (> 10% metachromatic blasts) without meeting the full criteria for systemic mastocytosis, notably lacking CD2/CD25 expression, D816V KIT mutation, and focal dense mast cell infiltrates." (PMID 40751871, 2025). "In contrast, in systemic mastocytosis, high KIT/CD117 expression is observed, but usually, there are no KIT gene mutations." (PMID 38275618, 2024). "Systemic mastocytosis (SM) is a rare clonal haematopoietic stem cell disease in which activating KIT mutations (most commonly KIT D816V) are present in virtually every (>90%) adult patient at similar frequencies among non-advanced and advanced forms of SM." (PMID 35626091, 2022). "Bone marrow biopsy was completed and—although perhaps higher sensitivity could have been achieved with allele-specific PCR for the assessment of D816V KIT mutation and CD25/tryptase staining—there were no major or minor criteria satisfied for the diagnosis of systemic mastocytosis." (PMID 37689672, 2023). "In humans, systemic mastocytosis with associated clonal hematological non-mast cell lineage diseases (SM-AHNMD) is a heterogeneous clinical entity, with a variable presence of KIT D816V in the malignant non-mast cell clone." (PMID 24788138, 2014).
cutaneous melanoma (103 papers, 2008 to 2026). A primary melanoma arising from atypical melanocytes in the skin. "In contrast, KIT mutations are relatively uncommon, occurring in only 1–3% of cutaneous melanomas and more frequently in mucosal, acral, and chronically sun-damaged subtypes." (PMID 41301010, 2025). "This entity is distinguished from classic cutaneous melanomas by a specific molecular profile, notably the c-KIT gene mutation observed in 35.5% of cases." (PMID 40978962, 2025). "Mutations in c-KIT, a tyrosine kinase receptor involved in melanocyte regulation, are common in acral lentiginous melanomas (23%) but rare in cutaneous melanomas (<2%), leading to KIT overexpression and tumorigenesis." (PMID 39859464, 2025). "Novel therapeutic approaches include immunotherapy and targeted therapy (BRAF/MEK or KIT inhibitors), although mutation profiles differ from cutaneous melanoma, with KIT and NRAS mutations more common than BRAF." (PMID 41002705, 2025). "This is consistent to current literature that BRAF, HRAS, KRAS or KIT mutations occur rarely in meningeal MCs and are more commonly observed in cutaneous melanoma." (PMID 41324772, 2025). "BRAF and NRAS mutations have been reported in 41% and 18% of human cutaneous melanomas, respectively, and KIT mutations in 8.6–25% of acral/mucosal/chronically sun-damaged skin melanomas." (PMID 38397192, 2024). "The alternative to ICI is targeted therapy aimed at driver mutations, with BRAF being the most prevalent mutation in cutaneous melanoma and c-KIT being the most prevalent mutation in mucosal melanoma." (PMID 39207855, 2024). "c-KIT mutations are most commonly seen in patients with mucosal or acral melanoma (15–20%) and in a about 2–3% of cutaneous melanomas that arise from chronic sun-damaged skin." (PMID 39207855, 2024). "SF3B1 and KIT have been shown to have a higher mutation rate in MM as compared to cutaneous melanoma, whereas BRAF and NRAS have a lower mutation rate in MM." (PMID 39416390, 2024). "Nevertheless, KIT mutation analysis is also important in cutaneous melanomas, as KIT-mutated cases can benefit from tyrosine kinase inhibitors." (PMID 37373134, 2023). "KIT alterations include amplifications or mutations, which are rare in cutaneous melanoma (about 3%), but relatively frequent in mucosal, acral and cutaneous melanoma with chronic sun damages (9–21% of cases)." (PMID 35008245, 2021). "Both the mutations and amplifications of c-KIT are uncommon in cutaneous melanomas (3–4%) but are enriched in acral (8.6–36%) and mucosal melanomas (9.6–39%) (KIT mutations are enriched in sinonasal mucosal melanomas, as opposed to anogenital)." (PMID 34831002, 2021). "KIT mutation occurs in 25% of acral melanoma, 22% of mucosal melanoma, and 8% of cutaneous melanomas." (PMID 33918490, 2021). "Meanwhile, reports on various ethnicities and geographic areas of the world reported that the incidence rates of KIT mutation in skin melanoma are highly variable but still considered very low based on the initial observations." (PMID 31848942, 2020). "In this cutaneous melanoma cohort KIT mutation frequency was found to be 34/79 (43.04%) with a significantly higher rate in acrolentiginous melanoma (ALM) as compared to UV-induced common variants (20/34, 58.8% versus 14/45, 31.1%, p = 0.014)." (PMID 31848942, 2020). "The relatively high KIT mutation rate in cutaneous melanoma in this central-European cohort justifies regular testing of this molecular target in this entity, not only in mucosal variants." (PMID 31848942, 2020). "The actual frequency of KIT mutation in the original 227 patient cutaneous melanoma cohort was 34/227, 14.9%." (PMID 31848942, 2020). "In the 34 KIT mutant skin melanoma cases 38 mutations have been detected because in two cases double mutations and in one case triple mutations occured." (PMID 31848942, 2020).
cutaneous melanoma (continued). "AM also has different oncogenic drivers from cutaneous melanoma, including inconstant KIT mutation rates (3–29%), CCND1 and CDK4 amplification, and deletion or mutations in different genes, such as CDK2NA, PTEN, NF1, and hTERT." (PMID 33344255, 2020). "Despite this good purpose, to date, only BRAF mutations have FDA approved therapies in advanced cutaneous melanoma, whereas KIT mutations have the tyrosine kinase inhibitors Imatinib as off-label prescription." (PMID 32695793, 2020). "The frequency of BRAF, NRAS and KIT mutations in CjM is more similar to cutaneous melanoma than uveal/mucosal melanoma." (PMID 31683701, 2019). "Other activating oncogenic events, including the gain-of-function mutations of KIT, are present in approximately 15% of mucosal melanomas but are rare in cutaneous melanomas." (PMID 30847022, 2019). "c-KIT, which is rarely mutated in cutaneous melanoma but more frequently in acral and mucosal melanomas, can be inhibited by dasatinib in cultured cells with an IC50 of approximately 60–80 nM." (PMID 30587121, 2018). "Somatic mutations in the KIT gene, which were identified in a small number of skin melanomas, appear to have a higher incidence in mucosal melanomas." (PMID 29796159, 2018). "NRAS was present in 28 of the 105 cutaneous melanomas (27%), and small numbers of KIT and MEK1 mutations were identified in cutaneous melanomas (3 and 4 cases respectively)." (PMID 28228113, 2017). "KIT somatic mutations are present mainly in mucosal melanoma, but they can also be found in cutaneous melanomas." (PMID 26863566, 2016). "This is particularly relevant in OMM, where mutation rates differ significantly from cutaneous melanoma; for instance, KIT mutations may occur in up to 25% of cases, while BRAF mutations are uncommon (<6%)." (PMID 41002705, 2025). "NRAS and KIT mutations are more frequently observed in PMME than in cutaneous melanoma." (PMID 37861097, 2024). "In contrast, the prevalence of NRAS and KIT mutations is higher in PMME than in cutaneous melanoma." (PMID 37861097, 2024). "Further, through the GEPIA database, in cutaneous melanoma, we examined the association between the ERBBs and 31 genes were close to each other and frequently altered and observed that all the genes except KIT, ALK, NTRK1, FGFR4, and MET were affected by the changes of some ERBB family members." (PMID 33732282, 2021). "In cutaneous melanoma, the mutation of KIT has been found more frequently for ALM." (PMID 31274706, 2020). "Similarly, in cutaneous melanomas, the incidence of KIT mutations ranges from 5.1% for non ‘sun-exposed’ patients to 9.8% for chronically ‘sun-exposed’ patients." (PMID 31683701, 2019). "In fact, c-KIT mutations have been shown to be more common in vulvar than cutaneous melanomas." (PMID 24535703, 2014). "Finally, chromosomal amplifications or activating mutations of the receptor tyrosine kinase KIT are found in 5–10% of cutaneous melanomas and confer independence from external growth factors, thus representing the most-upstream source of RAS pathway hyperactivation." (PMID 35234863, 2022). "Conversely, in CoM, the mutational spectrum overlaps with cutaneous melanoma, with frequent alterations in BRAF, NRAS, NF1, and KIT, offering actionable targets for personalised treatment." (PMID 41751395, 2026). "GNAQ and GNA11 mutations are prevalent in primary CNS melanoma but differ from cutaneous melanoma (CM), in which BRAF, NRAS, KIT, and NF-1 mutations are more common." (PMID 41536409, 2025). "The reported frequencies of mutations in cutaneous melanoma are 37–60% in BRAF, 13–25% in NRAS, 12% in NF1, 6–7% in MAP2K1, and 2–8% in KIT." (PMID 41295253, 2025). "Most cutaneous melanomas harbor activating mutations in BRAF or NRAS, but a distinct subset is defined by the oncogenic activation of KIT through somatic mutations." (PMID 41301010, 2025).
cutaneous melanoma (continued). "Biologically, these tumors exhibit low mutational burden with scarce BRAF (3–11%) mutations but more frequent KIT (22%) and NRAS (5–14%) aberrations, contrasting with the UV-driven mutation profiles seen in cutaneous melanoma." (PMID 41002705, 2025). "ARM are clearly distinguished from cutaneous melanomas by a lower frequency of BRAF mutations and a higher prevalence of c-KIT gene alterations, observed in around 35.5% of cases." (PMID 40978962, 2025). "The most frequent mutations in MM have been in SF3B1 (27%), KIT (18%) and NF1 (17%), a different pattern from cutaneous melanomas." (PMID 38275835, 2024). "In the publicly available GENIE dataset, looking exclusively at cutaneous melanomas shows that the specific mutation rates within primary tumors were 55 % for TERT, 40 % for BRAF, 7.2 % for KIT, 2.5 % for NRAS, and 1.9 % for CDH1." (PMID 38158497, 2024). "Aberrations in kinases such as proto-oncogene BRAF (exons 11 and 15; p.V600E), NRAS (exons 2 and 3; codons 12, 13, and 61), or KIT (exons 11, 13, 17, and 18) are key factors in human skin melanomas, regulating melanocyte proliferation survival and apoptosis." (PMID 38397192, 2024). "Mutations that are noted in mucosal melanoma include neurofibromin 1 (NF1), KIT, and splicing factor 3b subunit 1 (SF3B1); NRAS and BRAF mutations occur at far lower rates than traditional cutaneous melanoma." (PMID 39001457, 2024). "While the pathogenesis of MM has not been fully elucidated, certain mutational profiles seem to be characteristic—c-KIT tends to be found in increased frequency in MM whereas BRAF mutations are rare; the converse is true in cutaneous melanomas." (PMID 39416390, 2024). "Studies have shown that cutaneous melanomas are often linked to the BRAF V600E mutation, whereas AMMs are more frequently associated with a c-KIT mutation." (PMID 39449907, 2024). "Mucosal melanomas have a mutational profile characterized by KIT as the most frequent mutations (20–25% of cases), followed by BRAF and NRAS mutations (whose frequency is lower than that observed in cutaneous melanomas) and NF1 mutations." (PMID 39727691, 2024). "Acral melanomas have a higher frequency of triple-negative melanomas (45–58%) and consequently exhibit a higher frequency of KIT, GNAQ and TYRP1 mutations compared with cutaneous melanomas." (PMID 39727691, 2024). "The advent of molecular stratification and personalized medicine such as the current approaches for BRAF mutant cutaneous melanoma and KIT-mutant gastrointestinal tumors offer hope to these patients." (PMID 38417447, 2024). "The most common allelic variants (AV) in cutaneous melanoma tissues include BRAF, neuroblastoma RAS viral oncogene homolog (NRAS), mitogen-activated protein kinase kinase 1 (MAP2K1), and proto-oncogene c-KIT (KIT)." (PMID 35205608, 2022). "By comparison with cutaneous melanoma, mucosal melanoma has a decreased frequency of BRAF mutations (<10%) and an increased frequency of mutations of CD117 or c-KIT (40%), along with other somatic mutation (SF3B1, ATRX, ARID2, and SETD2)." (PMID 35334544, 2022). "Overall, alterations in BRAF, NRAS, NF1 and KIT are present in 93% of human cutaneous melanomas in a mutually exclusive pattern, although a small fraction of tumors harbor alterations in several of these genes." (PMID 35234863, 2022). "Commonly to cutaneous melanoma, mucosal mutations shows alterations in SF3B1, KIT, and NF1 and less frequently mutations in BRAF and NRAS." (PMID 33918490, 2021). "Mutations in KIT, NF1 and SF3B1 genes are more frequently seen in mucosal melanomas, while alterations to NRAS and BRAF genes are more common in cutaneous melanomas." (PMID 34209084, 2021). "Recently, epigenetic silencing of KIT gene by DNA methylation has been shown in cutaneous melanoma (CM)." (PMID 34639089, 2021). "The most frequent mutations in mucosal melanoma were in SF3B1 (27%), KIT (18%), and NF1 (17%), a pattern that is distinct from cutaneous melanomas." (PMID 33724703, 2021).
cutaneous melanoma (continued). "Three genes were enriched for mutations among mucosal melanomas in contrast to cutaneous melanomas: SF3B1 (27% vs. 2%), KIT (18% vs. 3%), and ATRX (9% vs. 1%)." (PMID 33724703, 2021). "On the contrary, in cutaneous melanomas, KIT is affected by CNAs in 6.7% of cases and by SNPs in 1.7% of cases." (PMID 33321993, 2020). "AM has different oncogenic drivers from the cutaneous melanoma, including fewer BRAF mutations (10–23%), inconstant KIT mutation rates (3–29%), CCND1 and CDK4 amplification, and deletion or mutations in different genes, such as CDK2NA, PTEN, NF1, and hTERT." (PMID 33344255, 2020). "On the contrary, aberrations in the KIT gene are more frequent in the sinonasal MM (7–17%) than in cutaneous melanoma and represent a new target." (PMID 33585548, 2020). "c-KIT mutations have been detected in almost 2–7% of conjunctival melanomas and they are mutually exclusive with NRAS and BRAF mutations, as in cutaneous melanoma." (PMID 31683701, 2019). "Approximately 90% of human cutaneous melanomas are driven in part by BRAF, RAS, NF1, and KIT mutations that confer constitutive mitogenic signaling through the MAPK pathway." (PMID 30188888, 2018). "The majority of human cutaneous melanomas are driven in part by constitutive activation of the MAPK pathway through mutation of genes such as BRAF, NRAS, NF1, KIT, GNAQ, and GNA11, often in a mutually exclusive pattern." (PMID 30188888, 2018). "Mucosal melanoma differs from cutaneous melanoma not only in terms of poorer clinical outcome but also on the molecular level having e.g. less BRAF and more frequent KIT mutations than cutaneous melanomas." (PMID 28380455, 2017). "The methylation profile of these genes and KIT was also investigated in a group of cutaneous melanomas." (PMID 26106605, 2015). "Molecular profiling may further support treatment tailoring by identifying actionable mutations (e.g., c-KIT, NRAS, or BRAF), although their prevalence is lower than in skin melanomas." (PMID 40875164, 2025). "Notably, KIT mutations are usually mutually exclusive of BRAF and NRAS mutations, which are the most common oncogenic drivers in cutaneous melanoma." (PMID 41301010, 2025). "Like in skin melanomas, KIT mutations do not commonly occur in CMs; however, KIT overexpression is more frequently observed, probably due to other events such as copy number alterations affecting the KIT locus." (PMID 37761808, 2023). "PTEN, KIT, and GNAQ/GNA11 mutations are among the rarest in cutaneous melanomas." (PMID 37373134, 2023). "Taking these results together, the approach pinpointed well-established driver genes also detected by frequency-based methods, but also likely drivers not readily detected by such methods, giving further support for GNAQ, KIT and SF3B1 driver mutations in cutaneous melanoma." (PMID 36396655, 2022). "Globally, the infrequent rate of BRAF V600E mutation observed in MM limits the efficacy of BRAF inhibitors, largely used in cutaneous melanoma, while the higher NRAS and c-KIT mutations rates make them potentially susceptible to NRAS and c-Kit target therapies." (PMID 35059992, 2022). "Although targeted therapy has evolved in the last years and significantly improved the prognosis of patients with cutaneous melanoma, its use in vulvar and vaginal melanomas is still limited by the different mutagenic profiles involving fewer BRAF mutations and more c-KIT, NF1 and SF3B1 mutations." (PMID 34209084, 2021).